CCL2 (C-C motif chemokine ligand 2)
Diseases named in the same sentence as CCL2 in open-access papers (continued):
Sharing a sentence is not in itself a finding about the gene and the disease.
brain inflammation (17 papers, 2007 to 2025). "It is well documented, that CCL2 released by astrocytes has an impact on cognitive dysfunction and brain inflammation." (PMID 33653365, 2021). "In order to further understand the functionality of CCL2 in mediating T-cell infiltration into the brain parenchyma, we induced brain inflammation with the stereotaxic injection of LPS in the cortex and striatum of mice." (PMID 22319587, 2012). "Brains were homogenized and intracranial levels of three cytokines known to be associated with and/or causative for HSV-1 mediated brain inflammation and that are also linked with the outcome of HSV-1 encephalitis, IL-6, CCL5 (Rantes) and CCL2 (MCP-1) were measured." (PMID 23082204, 2012). "In addition, astrocytes also enhanced microglial activation and boosted microglial TNF-α production in brain inflammation by producing proinflammatory molecules, for instance, C-C motif chemokine ligand 2 (CCL2) and granulocyte-macrophage colony-stimulating factor (GM-CSF)." (PMID 35087472, 2021). "An example of such a chemokine is CCL2, also known as monocyte chemoattractant protein 1 (MCP-1), which attracts monocytes and microglia to areas of brain inflammation." (PMID 38961424, 2024).
brain injury (17 papers, 2013 to 2025). Acute and chronic (see also brain INJURIES, CHRONIC) injuries to the brain, including the cerebral hemispheres, CEREBELLUM, and brain STEM. "Inflammatory mediators (IL-6, IL-12p40, HGF, M-CSF, CCL2, and IL-1RA) are associated with both altered consciousness and markers of brain injury." (PMID 38135686, 2023). "The expression of chemokines (e.g., CCL2, CCL5, CXCL10, and CXCL13) was also elevated in peripheral blood after brain injury and strongly associated with poor prognosis of TBI patients." (PMID 37208955, 2023). "Decreased levels of Ccl2 have been shown to be protective in models of traumatic brain injury and intracerebral hemorrhage." (PMID 31770590, 2020). "For example, signaling by chemokine (C-C motif) ligand 2 (CCL2) to the chemokine (C-C motif) receptor 2 (CCR2) is a key regulator of brain infiltration by monocytes after brain trauma." (PMID 32819386, 2020). "In transient insult-induced brain injury, microglia drive the infiltration and clonal expansion of CD8+ T lymphocytes via CCL2/CCL8 chemokines." (PMID 38914581, 2024). "Similarly, within clinical studies, increased levels of IL-6, TNF, IL-10, C-C motif chemokine ligand 2 (CCL2) and IL-8 peak within the first 2 days following brain injuries and then return to normal over several weeks." (PMID 33143727, 2020). "CCL2, CXCL1 and CX3CL1 all stimulate the proliferation and migrationof vascular endothelial cells, which indicates that these chemokines have similar actions onneovascularization after brain injuries." (PMID 23627909, 2013). "Chemotactic protein-1 (MCP-1, CCL2) and its receptor CCR2 are involved in the inflammatory response, and proinflammatory monocytes constitute the primary monocyte subgroups following brain injury,CCR2 is expressed high on proinflammatory monocytes while CX3CR1 is expressed low or not at all." (PMID 36793730, 2023).
cardiomyopathy (17 papers, 2013 to 2025). A disease of the heart muscle or myocardium proper. "The CCL2 has also been pointed out as a potential biomarker of cardiomyopathy in experimental and human T. cruzi infection." (PMID 28377930, 2017). "In the training dataset, the cardiomyopathy group's expression levels of CD14, CCL2, and SERPINA3 were significantly lower than the ones in the control group." (PMID 36148059, 2022). "In conclusion, with the intersection of multiple cardiomyopathy gene sets with different etiologies and WGCNA analysis and LASSO regression analysis, we screened out a key module (turquoise module) and three hub genes involved in cardiomyopathy progression (CD14, CCL2, and SERPINA3)." (PMID 36148059, 2022). "The hub genes (CD14, CCL2, and SERPINA3) can be used as markers to distinguish cardiomyopathy from non-cardiomyopathy individuals." (PMID 36148059, 2022).
fibromyalgia (17 papers, 2009 to 2025). A chronic disorder of unknown etiology characterized by pain, stiffness, and tenderness in the muscles of neck, shoulders, back, hips, arms, and legs. "CCL4 has long been associated with neuropathic pain, while muscle pain in fibromyalgia is associated with high levels of the related chemokine CCL2." (PMID 29927949, 2018). "This was surprising since selective elevation of MCP1/CCL2 serum levels have been previously reported in MMF patients, as well as in ME/CFS and fibromyalgia patients." (PMID 39058143, 2024).
myocardial ischemia (17 papers, 2012 to 2025). A disorder of cardiac function caused by insufficient blood flow to the muscle tissue of the heart. "CCL2 plays a crucial role in the recruitment of the Ly6Chigh monocyte into the infarcted area, and CCL2-deficient (CCL2−/−) mice have shown reduced monocyte infiltration, interstitial fibrosis, and ventricular dysfunction in response to myocardial ischemia compared to WT mice." (PMID 37445929, 2023). "CCL2 expression is commonly increased after myocardial ischemia." (PMID 37511318, 2023). "As one of the resident immune cells in the heart, during myocardial ischemia, B cells can release a variety of cytokines (including CCL2, CCL7, etc.)that chemoattract monocytes and neutrophils, thereby greatly increasing peripheral blood leukocytes myocardial infiltration." (PMID 36684609, 2022). "Interestingly vagal nerve stimulation (VNS), which decreases infarct size and adverse LV remodeling and HF in several experimental models, suppressed SP in a rat model of cardiac ischemia and decreased CCL2 and LIX plasma levels in the rat after IR injury." (PMID 27242392, 2016). "Interestingly, Tarzami and colleagues found a protective effect of CXCL2 dependent CCL2 expression in cardiac ischemia without reperfusion, a survival pathway in target cardiac myocytes themselves." (PMID 27242392, 2016).
neuropathic pain (17 papers, 2010 to 2025). Chronic pain caused by damage to nerve fibers. "Our findings demonstrate that EA suppresses spinal CCL2-driven microglial activation to produce its analgesic effects in neuropathic pain." (PMID 41009612, 2025). "CCL2 is considered an endogenous initiator of neuropathic pain by directly sensitizing nociceptors, exciting DRG neurons, and enhancing glutamate release of primary afferents and postsynaptic glutamate receptor function in the superficial dorsal horn." (PMID 35775484, 2022). "During pathogenesis of neuropathic pain, activated microglia produce and release a variety of pro-inflammatory cytokines (e.g., IL-1β, TNFα, IL-6, and CCL2) and BDNF to sensitize spinal neurons." (PMID 33739978, 2021). "Other studies have identified pharmacological interventions that prevent hyperalgesia development if CCL2 is neutralized prior to the neuropathic induction giving insight into an eventual CCR2-mediated treatment for neuropathic pain." (PMID 21143971, 2010). "We conclude that the anti-nociceptive effect produced by blocking upregulated DRG NIS-lncRNA in neuropathic pain likely results from inactivation of the Ccl2 gene, silencing of CCL2 protein expression, and reduction of neuronal excitability, particularly in medium and large neurons of injured DRGs." (PMID 35775484, 2022). "Furthermore, CCL2 neutralization can enhance the effectiveness of morphine in a mouse model of neuropathic pain." (PMID 32760393, 2020). "Thus, probably BET treatment is only effective on reducing pro-inflammatory mediators, such as TNF-α, CCL2, and CX3CR1, which are directly implicated in neuropathic pain." (PMID 31186006, 2019). "EE can relieve neuropathic pain by reducing inflammatory mediators, such as proinflammatory cytokines (IL-1β, TNF-α, IL-6) and chemokines (CCL2, CCL3), among others, increasing anti-inflammatory substances (IL-10, Arg-1, CX3CL1) in the periphery and CNS." (PMID 40190342, 2025). "In light of our research, we propose that CCL2/7/8/CCR1 and CCL7/8/CCR3 signaling are important elements in the modulation of neuropathic pain." (PMID 36611891, 2022). "The C-C motif chemokine ligand 2 (CCL2) is essential for glial cell activation inflammatory and neuropathic pain, which could be utilized as a therapeutic target for neuropathic pain." (PMID 41142152, 2025). "Of the 47 investigated proteins, 21 (cathepsin S, CCL2, CCL4, CCL16, CFIII, CXCL5, cystatin B, E-Selectin, Fas/TNFRSF6, follistatin, GDF-15, GH, ICAM1, IL8, KLK5, MMP2, MMP9, P-Selectin, sortilin, TIMP4 and VEGF) were detectable by multiplex SP-PLA in ≥ 95% of the neuropathic pain patient samples." (PMID 26914813, 2016).
Thrombocytopenia (17 papers, 2006 to 2024). A reduction in the number of circulating thrombocytes. "In addition, CCL2/MCP-1 and IL-8 are intimately related to hypotension, thrombocytopenia and hemorrhagic shock." (PMID 21206747, 2010). "A genetic study reported associations of genetic polymorphisms (the R/R genotype of FCGR2A p.R131H and the G/G genotype of CCL2 c.-2518 A > G) with thrombocytopenia; however, our study did not reveal an association of MICB and PLCE1 variants with thrombocytopenia." (PMID 37958261, 2023).
acute liver failure (16 papers, 2014 to 2025). Rapid deterioration of liver function causing encephalopathy and coagulopathy. "TGFβ1 is released into the circulation after acute liver failure and binds TGFβR2 in neurons, resulting in increased CCL2 expression and decreased CX3CL1 expression leading to microglial activation." (PMID 30940161, 2019). "We have previously demonstrated that CCL2 expression and secretion from neurons is central to the activation of microglia and subsequent pro-inflammatory cascade in the brain during acute liver failure." (PMID 30940161, 2019). "The results presented here suggest that, following acute liver failure, microglia activation via CCL2-induced signaling contributes to the neurological decline associated with hepatic encephalopathy." (PMID 25012628, 2014). "Therefore, the aims of this study were to assess the expression of CCL2 and its receptors in a rodent model of hepatic encephalopathy due to acute liver failure and to determine how CCL2 contributes to the neurological decline observed in this disorder." (PMID 25012628, 2014). "In addition to increased brain CCL2 expression, our data indicate an elevation of CCL2 in the circulation during the neurological complications of acute liver failure." (PMID 25012628, 2014). "TTP is upregulated in acute liver failure (ALF), and the mRNA stability of C-C motif chemokine ligand 2 (CCL2) and C-C motif chemokine ligand 5 (CCL5) is weakened by m6A modification, thus alleviating acute liver injury." (PMID 37020540, 2023). "Here, we report that TTP was upregulated in acute liver failure (ALF), resulting in decreased mRNA stabilities of CCL2 and CCL5 through promotion of N6-methyladenosine (m6A) mRNA methylation." (PMID 34877932, 2021). "In the current study, we present novel data indicating that neuron-specific knockout of TGFβR2 attenuated the expression of CCL2, increased CX3CL1 expression, inhibited microglia activation, and reduced neurological deficits during acute liver failure." (PMID 30940161, 2019). "Importantly, inhibition of CCL2 and CCL5 has been reported to reduce monocyte infiltration and alleviate acute liver failure." (PMID 34877932, 2021). "Further studies revealed that CCL2-mediated hepatocyte proliferation could yield a sufficient number of highly active and well-functioning hepatocytes, crucial for supporting Bioartificial liver (BAL) therapy in treating acute liver failure (ALF) in a porcine model." (PMID 41281752, 2025). "However, we were unable to show increased Ccl2 expression in microglia after BDL, suggesting that the presence of alternative sources of chemokines like neurons (as has been shown in acute liver failure), might additionally play a role in innate immune cell attraction to the brain." (PMID 37248507, 2023).
acute pancreatitis (16 papers, 2011 to 2024). An acute inflammatory process that leads to necrosis of the pancreatic parenchyma. "The increase in the CD68+CCR2+ population in the acute pancreatitis group at 24 hours favors the recruitment of these cells via CCL2/CCR2 axis into the lungs." (PMID 23110041, 2012). "Considering the increased levels of the CCL2 in the lung tissue of the acute pancreatitis groups and the immunohistochemistry data for F4/80 antigen, the macrophage populations in the lungs were further analyzed by adding another cell marker (CD68)." (PMID 23110041, 2012). "Furthermore, Ifnardel mice also showed an increase of the chemokine Ccl2 in acute pancreatitis." (PMID 26618925, 2015). "Both CCL2 and CXCL2 were reduced by D2 signaling in acute pancreatitis, and in mouse renal proximal tubule cells, D2 knockdown was associated with an increase in CCL2 production." (PMID 36757901, 2023).
head and neck squamous cell carcinoma (16 papers, 2009 to 2025). A squamous cell carcinoma that arises from any of the following anatomic sites: lip and oral cavity, nasal cavity, paranasal sinuses, pharynx, larynx, and salivary glands. "Blocking the CCL2/CCR4 axis in Tregs evokes an anti-tumor immune response in a model of head and neck squamous cell carcinoma while blocking of CCL2/CCR4 axis on CTLs could be detrimental as argued in the study." (PMID 34804061, 2021). "Moreover, expression of CCL2 induced by radiotherapy mediates the recruitment of CCR2+ Tregs in a mouse model of head and neck squamous cell carcinoma, thus diminishing the efficacy of radiotherapy, indicating that CCL2 may be a potential target to improve the efficacy of radiotherapy." (PMID 36077785, 2022). "Additionally, paracrine CCL2 from F. nucleatum-reprogrammed adipocytes upregulates SLC1A5 and SLC7A11 in head and neck squamous cell carcinoma (HNSCC), leading to glutathione (GSH) accumulation and cisplatin resistance." (PMID 41276817, 2025). "A groundbreaking report confirmed that high expression of CAF-specific VEGFA, PGE2S, COX2, EGFR, CCL2, and NANOG was considered as the culprit of CDDP resistance development in head and neck squamous cell carcinoma (HNSCC)." (PMID 36359776, 2022). "In a head and neck squamous cell carcinoma (HNSCC) murine model, researchers found that RT could upregulate CCL2 production and induce the CCR2-dependent accumulation of Tregs and TNF α-producing monocytes and macrophages, thereby playing an immunosuppressive role." (PMID 33789758, 2021). "In addition, pharmacological inhibition of CCL2/CCR4/Vav2/Rac1/MLC signaling pathway can effectively reduce the motility of cancer cells, thereby inhibiting local invasion and distant lymph node metastasis in head and neck squamous cell carcinoma (HNSCC) cells." (PMID 41341593, 2025). "Showed that the CCL2/CCR4 axis, not CCL2/CCR2, induced the signaling cascade responsible for cell motility and metastasis in head and neck squamous cell carcinoma." (PMID 36555280, 2022).
idiopathic pulmonary fibrosis (16 papers, 2013 to 2026). Idiopathic pulmonary fibrosis (IPF) is a nonneoplastic pulmonary disease that is characterized by the formation of scar tissue within the lungs in the absence of any known cause. "In idiopathic pulmonary fibrosis (IPF), alveolar epithelial cell injury leads to the release of interleukin-1 (IL-1), tumor necrosis factor-alpha (TNF-α), and chemokine CCL2." (PMID 41007870, 2025).
metastatic melanoma (16 papers, 2005 to 2025). A melanoma that has spread from its primary site to another anatomic site. "However, CCL2 has also been associated with a T cell infiltrated phenotype in human metastatic melanoma (MM), which complicates the understanding of CCL2 in cancer." (PMID 30126117, 2018). "A study looking at metastatic melanoma biopsies showed that up-regulation of several chemokines, including CCL2, CCL3, CCL4, CCL5, CXCL9, and CXCL10 could be correlated with the presence of T cells in the tumor." (PMID 34207884, 2021). "Therefore, CCL2 and miRNAs are potential prognostic factors and attractive targets for counteracting treatment resistance in metastatic melanoma." (PMID 26684239, 2016). "CCL2, also known as MCP-1, has been reported to bind CCR4 on cytotoxic T lymphocytes, resulting in their recruitment to the metastatic melanoma cells and inducing an immune-mediated protective role." (PMID 33466236, 2021). "C-C motif chemokine ligand 2 (CCL2) is a chemokine that regulates the growth and pro-invasive capability of metastatic melanoma cells." (PMID 31739477, 2019).